PCBP3 (poly(rC) binding protein 3)
Description:
Single-stranded nucleic acid binding protein that binds preferentially to oligo dC.
Synonyms: PCBP3-OT1; PCBP3OT; FLJ44028; ALPHA-CP3
Tractability: PROTAC: ubiquitination databases record sites on it; its protein half-life has been measured.
Gene: Protein-coding gene on chromosome 21 (45,643,694 to 45,942,454, forward strand). Ensembl gene ENSG00000183570.
Subcellular location: Cytoplasm
Subcellular location (Human Protein Atlas): Mitochondria; Nucleoplasm; Vesicles
Gene Ontology:
Molecular function: RNA binding; DNA binding; nucleic acid binding
Biological process: mRNA metabolic process; regulation of transcription by RNA polymerase II; viral RNA genome replication
Cellular component: cytosol; extracellular exosome; nucleus; cytoplasm
Genetic constraint (gnomAD): Loss-of-function variants: 17 observed, 36.27 expected, observed/expected ratio (o/e) 0.47, 90% interval 0.32 to 0.7. The upper end of that interval is the gene's LOEUF score, 0.7, which puts it in group 2 of 6, group 1 being the genes least tolerant of losing a copy. Missense variants: 344 observed, 442.18 expected, observed/expected ratio (o/e) 0.78, 90% interval 0.71 to 0.85. Synonymous variants: 147 observed, 166.98 expected, observed/expected ratio (o/e) 0.88, 90% interval 0.77 to 1.01.
Homologues: Orthologues: macaque PCBP3 (99% identical), guinea pig PCBP3 (98% identical), rat Pcbp3 (98% identical), dog PCBP3 (97% identical), mouse Pcbp3 (97% identical), pig PCBP3 (96% identical), chimpanzee PCBP3 (77% identical), Drosophila melanogaster mub (51% identical), zebrafish zgc:110045 (45% identical), Caenorhabditis elegans pes-4 (38% identical), Drosophila melanogaster ps (24% identical), Drosophila melanogaster Imp (19% identical), and 6 more. Paralogues in human: PCBP2 (71% identical), PCBP1 (65% identical), PCBP4 (52% identical), HNRNPK (32% identical), IGF2BP2 (29% identical), FUBP1 (28% identical), FUBP3 (27% identical), KHSRP (27% identical), NOVA2 (26% identical), IGF2BP1 (25% identical), IGF2BP3 (25% identical), NOVA1 (25% identical).
Diseases named in the same sentence as PCBP3 in open-access papers:
PCBP3 is named in the same sentence as 15 diseases in open-access papers, as found by Europe PMC text mining. Sharing a sentence is not in itself a finding about the gene and the disease. The quoted sentences say what the papers report.
pancreatic cancer (3 papers, 2021 to 2022). "PCBP3 was associated with favorable prognosis in pancreatic cancer." (PMID 35027621, 2022).
breast carcinoma (2 papers, 2018 to 2024). "A recent study of breast cancer highlighted the regulatory role of RNA binding by PCBP3 (paralog of PCBP1 along with PCBP2) on mRNA stability and induction of epithelial-mesenchymal transition (EMT)." (PMID 29335020, 2018). "It was found in our study that RBM47, PCBP3, FRG1, SRP72 and other RBPs may regulate the AS of ITGA6, ADGRE5, TNC and other genes and affect the EMT process of breast cancer cells." (PMID 38783078, 2024). "RBM47, PCBP3, FRG1, SRP72 and other RBPs might regulate AS of ITGA6, ADGRE5, TNC and other genes and affect the EMT process of breast cancer cells." (PMID 38783078, 2024). "By establishing the correlation network of differential RBPs and differential AS events, we found that RBM47, PCBP3, FRG1, SRP72, RBMS3 and other RBPs may regulate the AS of ITGA6, ADGRE5, TNC, COL6A3 and other cell adhesion genes, which may affect the EMT process of breast cancer cells." (PMID 38783078, 2024).
colorectal cancer (1 paper, 2026). A primary or metastatic malignant neoplasm that affects the colon or rectum. "Functional experiments demonstrated that silencing PCBP3 or NGRN significantly inhibited the proliferation and invasion of HCT116 colorectal cancer cells." (PMID 42271539, 2026). "Collectively, our findings identify PCBP3 and NGRN as promising prognostic biomarkers and potential therapeutic targets in colorectal cancer and provide new insights into the role of RNA metabolism in colorectal cancer progression and tumour immune regulation." (PMID 42271539, 2026).
Corneal astigmatism (1 paper, 2023). "By using a GWAS approach, SNPs near TJP2, PCBP3, CADM2, and TRPM3 were identified to be associated with myopia or refractive errors, and HMG20A and PPP2R2B were associated with axial length and corneal astigmatism, respectively." (PMID 37449273, 2023).
lung disease (1 paper, 2021). "Our present findings showing that PCBP3 plays an important role in myofibroblast activation and fibrogenesis and significantly extends our previous understanding by identifying an additional node of interaction between PCBP3-mediated posttranscriptional dysregulation and lung disease." (PMID 34603058, 2021).
lung fibrosis (1 paper, 2021). "This future direction may be important to better understand how PCBP3 regulates PFKFB3-mediated glycolysis in pulmonary fibrosis." (PMID 34603058, 2021). "Therefore, we identify PCBP3 as a protein involved in the regulation of glycolysis reprogramming and lung fibrogenesis and propose it as a therapeutic target for pulmonary fibrosis." (PMID 34603058, 2021). "However, one of the limitations of this study is that we didn’t knock out PCBP3/PFKFB3 in mice to verify their effects in lung fibrosis, which may be explored in the further research." (PMID 34603058, 2021). "To determine the functional impact of PCBP3-mediated regulation of PFKFB3 expression in lung fibrosis, we transfected lung fibroblasts with FLAG-PCBP3." (PMID 34603058, 2021).
pancreatic ductal carcinoma (1 paper, 2020). "A study of pancreatic ductal carcinoma showed that the content of PCBP3 protein in postoperative tissues was significantly related to the survival time of patients, and the prognosis of the group with lower PCBP3 protein content was worse." (PMID 33193718, 2020).
schizophrenia (1 paper, 2023). A major psychotic disorder characterized by abnormalities in the perception or expression of reality. "Relatedly, a CNV study of the etiological overlap between ASD and schizophrenia features PCBP3." (PMID 37120522, 2023).
cancer (2 papers, 2021 to 2022). A tumor composed of atypical neoplastic, often pleomorphic cells that invade other tissues. "Additionally, aberrant expression of PCBP3 and HSBP1 were significantly associated with cancer development and therapy resistance." (PMID 34212178, 2021).
PCBP3 also shares sentences with these, for which no sentence is quoted: tumor (3 papers); cervical cancer (1); myopia (1); prostate carcinoma (1); refractive error (1); type 1 diabetes (1).